BMI1 (BMI1 proto-oncogene, polycomb ring finger)
Diseases named in the same sentence as BMI1 in open-access papers (continued):
Sharing a sentence is not in itself a finding about the gene and the disease.
cancer (continued). "Indeed, Bmi-1 is a member of the polycomb repressor complex 1 that mediates gene silencing by regulating chromatin structure and is critical for self-renewal of both normal and cancer stem cells." (PMID 29765508, 2018). "Silencing of Bmi1 greatly decreased tumor growth of primary tumor xenografts, considerably inhibited the tumorigenic activity of secondary and tertiary tumorspheres and significantly reduced the number of cancer stem cells at the level of xenograft tumor tissue." (PMID 29156578, 2017). "Additionally, re-expression of the phosphorylatable but not non-phosphorylatable BMI1 rescued clonal growth in endogenous BMI1 silenced cancer cells leading us to speculate that CK2α-mediated phosphorylation stabilizes BMI1 and promotes its oncogenic function." (PMID 28270146, 2017). "Moreover, our findings using TCGA–HNSCC data also failed to reveal the differential expression of Bmi1 between cancer and normal epithelial and associations between Bmi1 expression and clinicopathological characteristics or prognosis." (PMID 29200967, 2017). "In addition, BMI1, through indirect mechanisms, can upregulate genes that promote cancer progression, such as the kinase Aurora A, and several genes involved in epithelial‐to‐mesenchymal transition and transforming growth factor‐β and epidermal growth factor/platelet‐derived growth factor pathways." (PMID 28079973, 2017). "According to the results of previous studies, expression levels of BMI1 in invasive bladder cancer were significantly higher than those detected in superficial bladder cancer, thereby showing a strong correlation with the clinicopathological features of this cancer type." (PMID 29220397, 2017). "This suggests that targeting Bmi1 may be an efficient way to prevent cancer recurrence." (PMID 27863490, 2016). "The structure of the PHC2–BMI1 complex we determined here provides the molecular basis to develop small molecule inhibitors of BMI1 activity and might pave the way towards novel anti-cancer therapeutics." (PMID 27827373, 2016). "Bmi-1 may also be involved in cancer metastasis and treatment resistance in some kinds of cancer." (PMID 27644439, 2016). "Hematoxylin and eosin staining showed that cancer cells in the control group grew well, with only small patches of necrosis, while cells in the Ad-Bmi-1i treated group had more patches of necrosis area, suggesting the direct killing effect of Ad-Bmi-1 is present." (PMID 27009837, 2016). "Furthermore, BMI1 cooperates with TWIST1 to promote cancer dedifferentiation and metastasis." (PMID 27225481, 2016). "Therefore, therapeutic targeting of BMI1 could help in the treatment of breast, prostate, colorectal and possibly other cancers, and overcome the disease recurrence." (PMID 27105531, 2016). "Therefore, the PODXL/Bmi1 signaling axis identified in this study may also play important roles in the chemoresistance and progression of other cancers besides OTSCC, which needs to be verified in future studies." (PMID 25915207, 2015). "In addition, PTC-209 exhibited an irreversible decrease in the sphere formation ability of primary colorectal tumors in vitro and tumor formation in vivo following a limited dilution assay, suggesting that inhibition of BMI1 has the potential to target chemo-resistant cancer-initiating cells." (PMID 26110620, 2015). "However, whether EMT inhibition by ERα is mediated through a direct/indirect upregulation of E-cadherin remains poorly understood, and further, the regulatory mechanism of Bmi1 in cancer cells and its role in metastasis are largely unknown." (PMID 26023734, 2015). "Because p16Ink4a-KO mice die of cancer long before they reach the age at which most normal mice experience a decline in SMG function, it is difficult to know whether dysregulation of the Bmi-1/p16Ink4a pathway is responsible for the aging-associated decline of SMG function." (PMID 25832744, 2015).
cancer (continued). "In addition to its effect on EC, BMI1 is also a pivotal factor in many other types of cancer." (PMID 25999024, 2015). "BMI1 is crucial for blood-cell development and the self-renewable potential of a variety of both normal and cancer stem cells, and may also play a role in cancer progression through regulation of both p16/INK4a and p14/ARF." (PMID 26110620, 2015). "In addition, Bmi-1 also downregulated PTEN by associating the PTEN locus and consequently activated the Akt/GSK3β pathway, ultimately induced EMT and cytoskeleton reconstruction, leading to enhanced invasiveness of cancer cells." (PMID 26452029, 2015). "Furthermore, Bmi-1 is also involved in the self-renewal of cancer stem cells, which may result in tumor initiation." (PMID 25295122, 2014). "Therefore, the cancer-promoting role of Sp1 may also be mediated by transcriptional activation of its downstream genes, such as Bmi1 and CENPH." (PMID 25099028, 2014). "Furthermore, down-regulation of Sp1 may suppress the acquisition of cancer stem cell phenotypes through the reduced expressions of SCTFs, including Bmi1, c-Myc and KLF4." (PMID 25099028, 2014). "Additionally, it was reported that BMI1 was involved in the metastasis of cancers." (PMID 23820733, 2013). "Furthermore, we speculated that the cytokine which suppresses miR-30e* expression could be derived from M1 macrophages, and thus performed Bmi1 expression in cancer cells treated with these cytokines produced by M1 macrophages." (PMID 24312366, 2013). "We tested this hypothesis by evaluating the effects of Bmi-1 inhibition by shRNA on DNA damage, apoptosis, mitochondrial membrane potential (ΔΨm) and apoptosis related protein for the purpose of a more improved cancer therapy." (PMID 22209830, 2012). "Bmi-1 may be a predictor of unfavorable prognosis of patients with these cancers." (PMID 23691455, 2012). "Importantly, overexpression of Bmi-1 could turn HNSCC-ALDH1− into cancer stem cell-like HNSCC-ALDH1+ cells." (PMID 20936121, 2011). "Additionally, Mel-18 and BMI1 may regulate tumorigenesis, cell migration and cancer metastasis via both p16- and AKT-dependent pathways." (PMID 20170541, 2010). "Moreover, SASVO3 exhibits properties of cancer stem cells, including that increased the abilities of sphere-forming, the number of side population cells, the potential of transplanted tumor growth and elevated expression of the stem cell marker Bmi1." (PMID 19917110, 2009). "TWIST and BMI1 act cooperatively to repress E-cadherin leading to the induction of EMT and stem-like properties of cancer cells." (PMID 41481650, 2026). "Thus, BMI1 could be a potential target for cancer prevention approaches." (PMID 41385756, 2026). "Our findings underscore the FOXA1/BMI1 axis as a key target for NPC treatment, offering insights into a potential new approach to improve patient outcomes in this aggressive cancer." (PMID 40623983, 2025). "BMI1 overexpression in NPC is significantly correlated with heightened malignancy, promoting cancer stem cell self-renewal and tumor invasiveness, thereby adversely impacting patient prognosis." (PMID 40623983, 2025). "As Bmi‐1 is found to be highly enriched in CD133‐positive CICs, it plays a vital role in maintaining the clonogenic potential of CD133‐positive cancer stem‐like cells in GBM by promoting self‐renewal and proliferation." (PMID 39791545, 2025). "Our previous results demonstrated that TAB2 promotes cancer stemness through NF‐κB pathway activation, as evidenced by enhanced sphere formation capacity and increased expression of stem cell markers SOX2 and BMI1." (PMID 40133221, 2025).
cancer (continued). "Cancer stem cell-related markers, CD44, ABCG2, BMI1, and KRT19, expression in subclusters from trajectory, indicated enhanced self-renewal capacity in SRGN-high malignant cells." (PMID 40384866, 2025). "A series of vitro experiments revealed that SRGN expression upregulated ABCG2, BMI1, and Nanog, enhancing the sphere-forming ability of HCC cells and increasing the population of cells with cancer stem cell-like characteristics." (PMID 40384866, 2025). "Together, these clinical and The Cancer Genome Atlas-based analyses highlight the prognostic significance of the VEGF‐A–BMI‐1 axis and further underscore the contribution of the miR‐200b–BMI‐1 pathway to OC progression." (PMID 41345229, 2025). "In bladder cancer, it directly interacts with the 3′-UTR regions of BMI-1 and E2F3, leading to their downregulation and resulting in decreased invasion, migration, and proliferation of cancer cells." (PMID 39859424, 2025). "First, we measured cancer stem-like phenotype markers, including NANOG, NOTCH, POU5F1(OCT3/4), SOX2, and BMI-1." (PMID 39728923, 2024). "This sponging leads to the subsequent upregulation of BMI1, KRAS, AKT3, KLF12, and NAMPT, along with several other cancer-promoting genes, thus promoting a more aggressive phenotype." (PMID 39039064, 2024). "We also show the unique role of the lncRNA DLEU2/ROR1 pathway in promoting the EMT and cancer stemness behavior via a mechanism closely engaging with TGF-β signaling, which drives EMT and CSC phenotypes via ALDH1 and BMI1 activation." (PMID 38296962, 2024). "The isolated cancer-stem like side population cells from NPC demonstrated increased expression of ABCG2 and the anti-apoptotic factor Bmi-1." (PMID 38254110, 2024). "On the other hand, inhibiting Bmi-1 rescinds CSC function and re-sensitizes cancer cells to chemotherapy." (PMID 36726797, 2023). "Cancer stem cell markers were also examined, which showed an upregulation in ALDH1A3, CD44, and WNT5A in amoeboid cells, and increased SOX2 and BMI1 in escaping cells." (PMID 37575281, 2023). "Data also suggest that the polycomb group protein named B lymphoma Mo-MLV insertion region 1 homolog (Bmi1) is a downstream target of Twist1 and is crucial for EMT and cancer metastasis." (PMID 38002001, 2023). "Studies have depicted that RNF2, BMI1, TRIM37, and other ubiquitinating genes were related to cancer progression." (PMID 37980168, 2023). "As previous studies have reported that the acquisition of invasiveness in cancer cells is accompanied by stemness features, we analyzed the expression of CD44 and BMI-1, universal markers for stem cells, using qRT-PCR and western blot analysis." (PMID 38137388, 2023). "Inhibition of BMI-1 also leads to DUB3-dependent Mcl-1 degradation, resulting in enhanced apoptosis of cancer cells." (PMID 37259388, 2023). "Bmi-1 has emerged as an attractive therapeutic target in CSC-focused, mechanism-based cancer treatments." (PMID 36726797, 2023). "B cell‐specific Moloney murine leukemia virus Integration site 1 (BMI1) and really interesting new gene 1B (RING1B) are PRC1 core components and play critical roles in the development of various cancers." (PMID 36737841, 2023). "By conducting a structure–activity relationship study that focused on exploring various linkers, we identified MS147, which preferentially degraded PRC1 components, BMI1 and RING1B, over PRC2 components: EED, EZH2, and SUZ12, in multiple cancer cell lines." (PMID 36737841, 2023). "Western blot analysis revealed that SQLE depletion substantially reduced the expression of cancer stemness‐related proteins, including CD44, BMI1, SOX2, and KIF‐4, in ALDHhigh primary HNSCC cells." (PMID 37490552, 2023). "Overall, this study provides a novel BMI1/RING1B degrader, which is a useful chemical tool to further investigate the roles of PRC1 in cancer, and a novel protein complex degradation strategy, which can potentially expand the degradable human proteome." (PMID 36737841, 2023).
cancer (continued). "Bmi-1 is a master regulator of stem cell self-renewal as part of the polycomb repressive complex 1 (PRC1) and has emerged as a prominent player in cancer stem cell biology." (PMID 36726797, 2023). "Analogously, PTC596 has been demonstrated to counteract EMT, in agreement with the literature reporting that BMI-1, the target of PTC596, promotes cancer migration and invasion by modulating the expression of EMT-related proteins." (PMID 38275623, 2023). "Migration/invasion abilities, cancer stemness and EMT phenotype of HNSCC CSCs are maintained by the Twist/Bmi1/Akt/β-catenin signalling pathway." (PMID 38002001, 2023). "miR-494-3p enhances core hallmarks of cancer by targeting several important tumor suppressor genes, such as PTEN, SOCS6 and BMI1." (PMID 35073936, 2022). "Paip2, Bmi-1, and H3F3B proteins are involved in tumor growth, and downregulation of Bmi-1 and H3F3B expression reduces cancer growth and xenograft development in JHU-22 miR-128 cells." (PMID 36793341, 2022). "Inhibition of Bmi-1 reduces the ubiquitination of myeloid cell leukemia sequence 1 (Mcl-1) by downregulating deubiquitinating enzyme (DUB3), resulting in cancer cell apoptosis." (PMID 35897796, 2022). "IIPA found that SFPQ interacts with many important proteins, such as YY1, RTN4, RICTOR, HDACs, BMI1, and HNRNPC, which are important in the development of cancer." (PMID 35707369, 2022). "CBX8, BMI1, and RNF2 are interaction proteins that maintain transcriptional repression of hundreds of cancer growth and signaling-related genes." (PMID 35813444, 2022). "Our findings of the role of BMI1/RAD51 axis in reducing RS and mediating therapeutic resistance in breast CSCs open new ways to treat cancer." (PMID 35110528, 2022). "The first BMI1 inhibitor PTC‐209 was reported in 2014,14 which showed promising anti‐cancer effect in pre‐clinical model of several types of tumours." (PMID 35794816, 2022). "There were also significant inverse correlations between BMI-1 and PHLPPs, especially PHLPP1, in normal and cancer endometrial tissue samples." (PMID 36497428, 2022). "There are two well-characterized PcG proteins, the BMI1 and EZH2, which are required for the regulation of the PRC activity but are also known to display oncogenic functions in several cancers." (PMID 36289829, 2022). "We also assessed the correlation between BMI1 expression and immune checkpoint-related molecules, including PD-L1, Galectin 9, HVEM, and IDO1, all of which are important marker genes for cancer immune therapy." (PMID 36199791, 2022). "PCGF4 (also known as BMI-1), the best-studied PRC1 gene in cancer, was one of the first PcG genes found in mammals and has been defined as a proto-oncogene that cooperates with the c-Myc oncoprotein to promote tumorigenesis." (PMID 36076977, 2022). "Among the selected cancer stemness genes, we found that TERT, MYC, CD44, BMI1, ABCB1 and ABCG2 were highly expressed in OCM1 cells compared to their expression in C918 cells, whereas the expression of ZEB1 was opposite to that of the stemness genes." (PMID 35404029, 2022). "One of the specific BMI1 inhibitors, PTC-209, displays high potency in repressing the growth of some types of cancer cells." (PMID 36199791, 2022). "Intriguingly, NEAT1 concomitantly increased the cancer stemness of TNBC cells and upregulated the expression of BMI1, OCT4, and SOX2." (PMID 35054896, 2022). "Taken together, our findings reveal that the inhibition of BMI-1 induces Mcl-1 destabilization through downregulation of DUB3, resulting in the induction of cancer cell death." (PMID 34576269, 2021).
cancer (continued). "CSC markers ALDH1A1, CD44, BMI1, OCT4, SOX2, and CD133 and their effects on cancer stemness, metastasis, prognosis, chemo/radiotherapy resistance and recurrence have been studied in HNSCC by our group and other researchers." (PMID 34359786, 2021). "The Shh pathway stimulates CSC self-renewal of a variety of cancers by inducing the expression of several stemness-related genes, including c-MYC, BMI1, Nanog, SOX2, and OCT4." (PMID 33499351, 2021). "High levels of BMI-1 have been found in both FOSCC and HNSCC with possible prognostic implication and future new treatment avenues in both cancers." (PMID 35053051, 2021). "The identification of BMI1 as a proto-oncogene that cooperates with MYC to promote B and T-cell lymphomas was the first evidence for the involvement of PcG genes in cancer development." (PMID 33804165, 2021). "Therefore, BMI-1 as a significant prognostic marker may be an effective target for cancer therapy." (PMID 34576269, 2021). "Other studies have shown that the other two transcription factors (BMI1 and c­JUN) are dysregulated in a variety of cancers and inhibit PTEN transcription." (PMID 34006834, 2021). "Current reports have documented that miR-203 is a stemness-inhibiting miRNA owing to its modulation of stemness properties through regulating the expressions of various targets in different types of cancers, including SOCS3, survivin, Bmi-1, and GATA6." (PMID 34539782, 2021). "Many small-molecule BMI-1 inhibitors, such as PTC-209, PTC-028, and PTC596, suppress self-renewal ability, tumor growth, and cancer invasion." (PMID 34576269, 2021). "Stemness is responsible for initiating metastasis and cancer recurrence, and miRNAs are involved in the maintenance of the cancer stem cell via targeting main signaling pathways such as WNT/β-catenin, NOTCH, NF-kB, PI3K/AKT/mTOR, BMI-1, and STAT3." (PMID 34846108, 2021). "In this study, we provided a model showing that LSD1 was overexpressed in HNSCC cancer cells and conferred CSC-like features mediated through Bmi-1 expression to them." (PMID 34689153, 2021). "Here, we reported that abridged miR-135a expression in OS cells and tissues, and its expression is inversely correlated with the expression of BMI1 and KLF4, which are described as oncogenes in several cancers." (PMID 33828977, 2021). "Recent studies have revealed that the PCGF family of proteins (PCGF1 (Nspc1), PCGF2 (Mel-18), PCGF3, PCGF4 (Bmi1), PCGF5 and PCGF6 is robustly elevated in diverse human cancers and promotes cancer progression." (PMID 34148069, 2021). "qRT‐PCR showed that circFAT1 KD significantly inhibited the expression of the cancer stemness‐related genes, including SOX2, KLF4, MET, BMI1, CD24, OCT4, and ALDH1, in ALDHhigh SCC23 cells." (PMID 34258151, 2021). "Additionally, it may be interesting to evaluate BMI1 expression in TAMs of various human cancers." (PMID 33993198, 2021). "As expected, PTC596 and knockdown of BMI-1 decreased the CSC population in human renal (Caki) and cervical (HeLa) carcinoma." (PMID 34576269, 2021). "The levels of cancer stemness-related genes (ABCG2, BMI1, NANOG, KLF4, and OCT4) mRNA and proteins (ABCG2, Oct4, Bmi-1, and CD44) expression were downregulated with treatment of STF-31 in HBx-expressing MHCC-97H cells." (PMID 32168902, 2020). "IHC staining of tumor sections revealed stronger cancer stemness markers (anti‐CD44, Twist, and Bmi1) and higher proliferative activity (anti‐Ki67) in tumor lesions stably expressing WT or Q311E." (PMID 32979859, 2020). "The impact of EGCG on histone methylation has so far been analyzed from the level of cancer cells and polycomb group (PcG) protein, particularly EZH2, but also Suz12, Mel18 and Bmi-1." (PMID 32429384, 2020). "Our analyses focused on several key NMPs including SATB1/2, SAFB1/2, EZH2, SUZ12, BMI1, PCL3, RAE28, and CTCF, as these NMPs have been shown to be aberrantly expressed in cancers." (PMID 33124191, 2020). "Thus, function of BMI‐1 in cancer may be cell‐context dependent." (PMID 31863623, 2020).